CD40 (CD40 molecule)
Diseases named in the same sentence as CD40 in open-access papers (continued):
Sharing a sentence is not in itself a finding about the gene and the disease.
cerebral toxoplasmosis (3 papers, 2010 to 2023). Infections of the brain caused by the protozoan toxoplasma gondii that primarily arise in individuals with immunologic deficiency syndromes (see also aids-related opportunistic infections). "Thus, CD40−/− mice are susceptible to ocular and cerebral toxoplasmosis despite upregulation of key mediators of host protection: IFN-γ, TNF-α and NOS2." (PMID 21217818, 2010). "These cells required PKR signaling to kill the parasite in response to stimulation via CD40, a molecule that promotes protection against ocular and cerebral toxoplasmosis." (PMID 23990781, 2013). "While CD40 likely functions in synergy with IFN-γ to enhance resistance to T. gondii in vivo, the role of PKR as a link between CD40 and killing of T. gondii via the autophagy pathway may contribute to increase the resistance to ocular and cerebral toxoplasmosis." (PMID 23990781, 2013). "Thus, CD40 is critical for control of ocular and cerebral toxoplasmosis." (PMID 21217818, 2010). "CD40 and its ligand CD154 are central for protection against ocular and cerebral toxoplasmosis and CD40 ligation activates macrophages and microglia to acquire anti-T." (PMID 23990781, 2013).
cholangiocarcinoma (3 papers, 2007 to 2024). A carcinoma that arises from the intrahepatic biliary tree (intrahepatic cholangiocarcinoma) or from the junction, or adjacent to the junction, of the right and left hepatic ducts (hilar cholangiocarcinoma). "Functional deficiency of CD154, the ligand for CD40, leads to a failure of clearance of biliary tract infections and a predisposition to cholangiocarcinoma implying a direct link between TNF receptor-mediated apoptosis and the development of cholangiocarcinoma." (PMID 21103345, 2010). "Second, strong expression of CD40 was observed in tumor samples from half of patients with cholangiocarcinoma." (PMID 39845973, 2024). "We have demonstrated that cholangiocarcinoma cells express CD40 and like primary cholangiocytes are exquisitely sensitive to CD154 mediated apoptosis." (PMID 21103345, 2010). "Primary cholangiocytes and cholangiocarcinoma cells intriguing seemed to express low levels of CD40 but high levels of Fas." (PMID 21103345, 2010). "We report that cholangiocarcinoma cells express functional CD40 and undergo apoptosis when stimulated with soluble trimeric CD154." (PMID 21103345, 2010). "One of the most interesting findings in this study was that despite the apparent low levels of CD40 on the cell surface, all of the cholangiocarcinoma cell lines nevertheless under went high levels of apoptosis." (PMID 21103345, 2010). "CD40/CD154 therapy in cholangiocarcinoma could work in two ways; by stimulating anti-tumour responses in leukocytes, and by the indirect promotion of cell death via CD40-dependent induction of FasL." (PMID 21103345, 2010). "This prompted us to investigate whether CD40 is expressed in cholangiocarcinoma and if so whether it is functional and therefore a potential therapeutic target." (PMID 21103345, 2010). "The increased levels of CD40 seen in diseased tissue and cholangiocarcinoma could be explained by high local levels of proinflammatory cytokines such as TNFα and IFN-γ at sites of persistent chronic inflammation." (PMID 21103345, 2010). "A similar mechanism could be operating in these cholangiocarcinoma cells that are resistant to direct Fas ligation but die in a Fas-dependent process after CD40 ligation." (PMID 21103345, 2010). "Thus the functional elements of the CD40 death-inducing mechanism are intact in cholangiocarcinoma." (PMID 21103345, 2010). "In this study we have shown that cholangiocarcinoma cells lines are resistant to Fas–mediated killing but show sensitivity to CD40 mediated apoptosis suggesting that CD154 therapy might be effective in the treatment and management of cholangiocarcinoma." (PMID 21103345, 2010).
chronic hepatitis B (3 papers, 2013 to 2018). "The percentage of CD19+ B cells significantly increased in chronic hepatitis B patients and CD40 expression levels on the CD19+ B cell surface in chronic HBV infection decreased compared with those in the healthy controls (P<0.05)." (PMID 23407366, 2013).
dementia (3 papers, 2015 to 2023). Loss of intellectual abilities interfering with an individual's social and occupational functions. "Consistent with our findings, XIN1, PECAM1, CD40, and JAMA were also reported to be differentially expressed in the plasma of subjects with dementia compared with MCI." (PMID 37175824, 2023).
diabetic nephropathy (3 papers, 2017 to 2024). "In another study where kidney biopsies from patients with diabetic nephropathy were obtained, tubular expression of CD40 and infiltrating CD40L-expressing cells were significantly upregulated." (PMID 33202988, 2020). "In a study investigating diabetic nephropathy, advanced glycation end-products (AGEs) are used to mimic diabetic conditions and AGEs lead to up-regulation of TGF-β1, CD40, and IL-17 in cultured human podocytes where co-stimulation of IL-17 and CD40L strongly activates TGF-β1 and CD40 expression." (PMID 33202988, 2020).
diabetic neuropathy (3 papers, 2018 to 2025). A chronic, pathological complication associated with diabetes mellitus, where nerve damages are incurred due to diabetic microvascular injury involving small blood vessels that supply these nerves, resulting in peripheral and/or autonomic nerve dysfunction. "Taken together, the association of CD40 with the proportion of thrombosed capillaries in diabetic neuropathy underpinned the interactions between these two networks of inflammation and thrombosis in the pathogenesis of microangiopathy leading to nerve degeneration." (PMID 29549140, 2018). "This study demonstrated the three key molecular signatures of microangiopathy-mediated diabetic neuropathy downstream of CD40: HIF-1α, MK2 and PTEN." (PMID 29549140, 2018). "There are indications that CD40 as well as CSF-1 is elevated in painful diabetic neuropathy." (PMID 41272580, 2025). "We chose to investigate the relationship between HIF-1α, MK2 and PTEN, and CD40 as they were upregulated in the endothelial cells of sural nerve microvasculatures and were all major determinants of microangiopathy and nerve morphometry in diabetic neuropathy." (PMID 29549140, 2018).
E. coli infection (3 papers, 2016 to 2021). "In contrast, chicks that received 25 μg and 50 μg of CpG-ODN demonstrated significantly enhanced MHCII-expressing APCs, CD40 expression on these APCs and T-cell populations that correlated with their ability to resist E. coli infection." (PMID 32411791, 2020). "In monocytes from TSC1 KO mice, the expression of CD40 is lower than in WT mice after E. coli infection, suggesting that the decreased expression of CD40 may lead, at least partially, to an ineffective activation of T cells." (PMID 27746591, 2016).
endometriosis (3 papers, 2021 to 2022). The growth of functional endometrial tissue in anatomic sites outside the uterine body. "The percentages of CD40-positive DCs and CD86-positive DCs were declined in the mice with endometriosis, but rhIL-37 treatment increased the percentage of them." (PMID 34429116, 2021). "Here, rhIL-37 treatment significantly increased the proportion of CD40-, CD80-, CD86-, and MHC II-positive DCs in the blood of the mice with endometriosis, suggesting that rhIL-37 promoted DCs maturation in endometriosis." (PMID 34429116, 2021). "In addition, we found that M2 macrophages in endometriosis displayed pro-inflammatory signatures that expressed CD40 and CD64, indicating a hybrid of M1 and M2 cell profiles within endometriosis lesions." (PMID 34233737, 2021).
focal segmental glomerulosclerosis (3 papers, 2016 to 2026). A renal disorder characterized by sclerotic lesions in the glomeruli. "Recent studies have also implicated altered regulation of the CD40 axis and generation of pathogenic activating anti-CD40 antibody for the generation of podocyte injury in focal segmental glomerulosclerosis (FSGS) recurrence after kidney transplantation." (PMID 27818660, 2016). "Recent insights suggest that combining suPAR levels with the detection of nephrin or CD40 autoantibodies in patients with focal segmental glomerulosclerosis (FSGS) could be particularly valuable, aiming to develop a kidney disease–specific composite scoring system." (PMID 41480757, 2026).
glomerulonephritis (3 papers, 2012 to 2018). A renal disorder characterized by damage in the glomeruli. "Finally, a deficiency of A20 leads to an hyperactivation of B cells after BCR, LPS or CD40 activation and to the spontaneous production of autoantibodies but, similar to Carabin deficiency, an A20 defect is associated with the development of glomerulonephritis after TLR9 stimulation." (PMID 23109291, 2012).
helminth infections (3 papers, 2018 to 2021). "Interference with CD40 upregulation in inflammatory DCs could impact the adaptive response to the infection, as CD40 participates in the induction of Th1 and Th2 responses against helminth infections." (PMID 31570562, 2019). "In addition to lowering Th1 response, an increased Th2 polarization could also be related to moderately increased expression of CD40 on DCs upon stimulation with ES L1, as it was shown that CD40 is critically involved in the induction of Th2 cells by DCs, especially during helminths infection." (PMID 29416536, 2018). "In MS patients with helminth infections, there is a compensatory abundance of IL-10-producing B cells through a mechanism that is largely dependent on the Inducible T cell costimulator ligand (ICOSLG)-pathway and not on the CD40, CD80 or CD86 pathways." (PMID 34122439, 2021).
kidney transplant (3 papers, 2011 to 2022). A surgical procedure in which one or both kidneys from a donor are implanted into a recipient. "Iscalimab (CFZ-533), an IgG1 anti CD40 antibody reported positive data in a phase 2 study of iscalimab versus a standard of care (SOC) arm containing the calcineurin inhibitor tacrolimus (TAC) in de novo kidney transplant recipients." (PMID 35464470, 2022). "We searched pubmed for studies reporting the prevention of kidney transplant rejection in nonhuman primates utilizing either anti CD40 or anti CD40L (CD154) treatment." (PMID 35464470, 2022).
liver cancer (3 papers, 2007 to 2021). An epithelial or non-epithelial malignant neoplasm that arises from the liver. "Immunohistochemistry demonstrated co-localisation and enhanced expression of C4BP and CD40 in human liver cancers." (PMID 17225862, 2007). "In addition to infiltrating immune cells, Bregs also directly interacted with liver cancer cells through the CD40/CD154 signaling pathway to enhance HCC growth and invasion, indicating that disruption of tumor-Breg interactions might be a potential therapeutic strategy to treat HCC." (PMID 33193391, 2020).
mastitis (3 papers, 2013 to 2025). Inflammation of breast tissue during lactation or postpartum due to an obstructed duct or infection. "In both S. aureus-positive and S. chromogenes-positive cows, the DE snoRNAs were correlated with several immune and inflammatory genes (e.g., IL1R, IL18R1, STAT3, NFKB2, MYD88, VEGFA and CD40), all of which have been reported in several studies to be associated to mastitis." (PMID 40936092, 2025). "In the case of the cytokine–cytokine-receptor interaction pathway, other genes, such as CD40, IL1RN, CXCR1, TNFRSF6B, and CCL19, were found to be involved in mastitis defense or immune response, as all these genes were upregulated in the mastitic cows based on their FC values." (PMID 35723402, 2022). "Moreover, CD40 and TREM1 signaling pathways appear as the most interesting candidates that likely provide the link between TLR2- and NLR-mediated signal transduction determining optimal host defence during mastitis." (PMID 24341851, 2013).
migraine (3 papers, 2011 to 2025). "Instead, CD40 on CD14‐CD16+ monocyte (PIVW: 0.034, ORIVW: 0.965, 95% CI: 0.933‐0.997) and CD8 on Effector Memory CD8+ T cell (PIVW: 7.24×10−4, ORIVW: 0.921, 95% CI: 0.878‐0.966) were found to reduce the risk of migraine." (PMID 40641356, 2025). "Other pathways, such as the inflammatory CD40 property, may be involved in the inflammatory process of migraine." (PMID 21331754, 2011).
neuropathy (3 papers, 2016 to 2022). A disorder affecting the nervous system that manifests with pain, tingling, numbness, and/or muscle weakness. "Biochemical analysis revealed time-dependent upregulation of mRNA and/or protein levels of TLR2 and TLR4 and MyD88 and TRIF adaptor molecules, which was paralleled by an increase in IBA-1/CD40-positive cells under neuropathy." (PMID 26962463, 2016). "Summing up, in light of their upregulation over the course of pain, both TLR2 and TLR4 may indeed play a significant role in neuropathy, which could be linked to the observed activation of IBA-1/CD40-positive cells." (PMID 26962463, 2016).
pemphigus (3 papers, 2017 to 2022). Pemphigus is a group of rare autoimmune diseases that cause blistering of the skin and mucous membranes (mouth, nose, throat, eyes, and genitals).This conditioncan occur at any age, but often strikes people in middle or older age. "Involvement of CD40/CD40LG levels was observed in the pathogenesis of pemphigus.Upregulation of both the receptor and the ligand has been reported in lesionalskin and the serum of patients with active PV and PF." (PMID 32639508, 2020). "A role for CD40, CD40LG andBAFF polymorphisms in pemphigus finds support in studies ofprotein or mRNA levels in PF and PV, and in the effects of these molecules andtheir genetic variants in homeostasis, in inflammation, and ADs." (PMID 32639508, 2020).
periodontitis (3 papers, 2016 to 2023). An acute or chronic inflammatory process that affects the tissues that surround and support the teeth. "Meanwhile, RT-qPCR data revealed approximately threefold higher CD40 and TRAF6 gene expression in periodontitis compared with the healthy group." (PMID 37261283, 2023). "Western blotting results further confirmed the upregulation of CD40 and TRAF6, both of which showed a nearly 1.5-fold increase in the periodontitis group." (PMID 37261283, 2023). "Consistently, immunofluorescence staining also exhibited higher expression of CD40 and TRAF6 in the gingiva with periodontitis." (PMID 37261283, 2023). "To investigate the variable expression of CD40 and TRAF6 in healthy individuals and patients with periodontitis, we harvested the gingival samples separately." (PMID 37261283, 2023).
pheochromocytoma (3 papers, 2019 to 2023). "In this study, we show that recently developed intratumoral application-based immunotherapy using mannan-BAM, TLR ligands, and anti-CD40 antibody (MBTA therapy) efficiently suppresses tumor growth in a murine bilateral pheochromocytoma model." (PMID 34439097, 2021). "In conclusion, we showed that intratumoral immunotherapy based on the application of mannan-BAM, TLR ligands, and anti-CD40 antibody (MBTA therapy) exhibits the potential to suppress tumor growth in a murine bilateral pheochromocytoma model." (PMID 34439097, 2021). "Combined mannan-BAM, TLR ligand, and anti-CD40 antibody-based intratumoral immunotherapy (MBTA therapy) previously resulted in the complete eradication of murine subcutaneous pheochromocytoma and demonstrated a systemic antitumor immune response in a metastatic model." (PMID 34439097, 2021).
preeclampsia (3 papers, 2012 to 2024). Preeclampsia is a hypertensive disorder of pregnancy that is characterized by new-onset hypertension with proteinuria presenting after 20 weeks of gestation, and depending on mild or severe forms may initially present with severe headache, visual disturbances, and hyperreflexia. "All robustly associated proteins, except CD40 for gestational hypertension and CSTB for preeclampsia, had directionally consistent associations with the other HDP subtype (eTables 8-9 in Supplement 2)." (PMID 38170504, 2024). "Robust associations (ie, directional consistency across all sensitivity analyses) were observed for 4 of 8 proteins associated with gestational hypertension (CD40, ECP, Gal-3, and NT-proBNP), and 2 of 4 proteins associated with preeclampsia (CSTB and HSP27)." (PMID 38170504, 2024). "The endothelial cell dysfunction observed in preeclampsia (PE) may be induced by CD40/CD40L signaling." (PMID 22510585, 2012). "Primary analyses identified 10 proteins reflecting pathways with potential roles in the development of HDPs, 6 of which were robust to sensitivity analyses for gestational hypertension (CD40, ECP, Gal-3, NT-proBNP) or preeclampsia (CSTB, HSP27)." (PMID 38170504, 2024). "Expression of immune checkpoints are also increased in the pro-inflammatory state of preeclampsia (PD-1/PD-L1 system, TIM-3, CD40/CD40L)." (PMID 38239507, 2023). "CD40 and ECP, although only measured in fewer than 100 participants each, were higher among participants with preeclampsia vs no HDPs (eTable 16 in Supplement 2)." (PMID 38170504, 2024).
pulmonary fibrosis (3 papers, 2020 to 2026). Chronic progressive interstitial lung disorder characterized by the replacement of the lung tissue by connective tissue, leading to progressive dyspnea, respiratory failure, or right heart failure. "Activation of CD40 and CD40L in pulmonary fibrosis causes fibroblast aggregation, proliferation, and expression of IL-6, IL-8, ICAM-1, and VCAM-1, causing collagen deposition and pulmonary interstitial changes leading to fibrosis finally." (PMID 32337277, 2020). "Overexpression of CXXC5 inhibited the progression of bleomycin-induced pulmonary fibrosis in mice by inhibiting the CD40/CD40L signaling pathway, which is possibly a new target for the treatment of pulmonary fibrosis." (PMID 32337277, 2020). "Additionally, CXXC5 exerts an antifibrotic effect by inhibiting CD40/CD40L during the development of bleomycin-induced pulmonary fibrosis in mice." (PMID 39806388, 2025). "Therefore, we conclude that overexpression of CXXC5 inhibits the development of pulmonary fibrosis by downregulating the CD40/CD40L pathway." (PMID 32337277, 2020). "Thus, CXXC5 overexpression inhibited the activation of the CD40/CD40L signaling pathway in a mouse model of pulmonary fibrosis." (PMID 32337277, 2020). "CD40 deficiency also significantly exacerbated TAC-induced pulmonary leukocyte infiltration (such as total CD45+ cells, Mac2+ cells and CD3+ cells), ∼1.7-fold more pulmonary fibrosis, and pulmonary vessel remodeling, as well as the consequent right ventricular hypertrophy." (PMID 41905182, 2026). "Studies have shown that blocking the CD40/CD40L pathway attenuated radiation-induced oxidative stress and immune-induced lung damage and pulmonary fibrosis." (PMID 32337277, 2020). "Based on the results of cell and animal experiments, we found a significant increase in CD40 and CD40L in the model of in vitro and in vivo pulmonary fibrosis and a significant decrease in CD40 and CD40L when CXXC5 was overexpressed." (PMID 32337277, 2020). "CXXC5 inhibits pulmonary fibrosis and transformation to myofibroblasts by negative feedback regulation of the CD40/CD40L pathway." (PMID 32337277, 2020). "Therefore, we hypothesize that CXXC5 may participate in the development of pulmonary interstitial fibrosis through the CD40/CD40L pathway and explore the role of the CXXC5/CD40/CD40L pathway in an in vitro and in vivo fibrosis model." (PMID 32337277, 2020). "We conducted further studies to explore whether CXXC5 exerted antifibrotic effects through the negative regulation of CD40/CD40L and found that CD40 and CD40L were upregulated in the pulmonary fibrosis model both in vitro and in vivo, but CD40 and CD40L were downregulated after CXXC5 overexpression." (PMID 32337277, 2020).